DAPK1 (death associated protein kinase 1)
Diseases named in the same sentence as DAPK1 in open-access papers (continued):
Sharing a sentence is not in itself a finding about the gene and the disease.
tumor (continued). "In most cases (37/43 genes), methylation was more frequent in cell lines than primary tumours, however for 6 genes this pattern was reversed (ZNF215: 21% and 42% respectively, DAPK1: 4% and 39%, EPHA3 13% and 32%, SMARCB1: 8% and 27%, EPS8 4% and 21% and MCM2: 0% and 21%)." (PMID 19493342, 2009). "They postulated downregulation of DAPK-1 by hypermethylation, as immunohistochemical staining was negative in tumour samples with DAPK-1 methylation." (PMID 17133271, 2006). "Finally, clinical applicability may be limited by tumor heterogeneity and variable epigenetic landscapes in HGSOC patients, which could impact the efficacy of DAPK1 restoration." (PMID 40563561, 2025). "Furthermore, Xing M demonstrated that activation of MAPK signaling pathway resulted in upregulation of tumor-promoting genes (e.g. VEGFA, MET, HIF1A, UPA, UPAR, TGFB1, and TSP1) as well as downregulation of tumor suppression and thyroid genes (e.g. TIMP3, SLC5A8, DAPK1, NIS, TSHR, and TPO)." (PMID 35600399, 2022). "However, BRCA1 functions differently as compared to DAPK1; BRCA1 is a tumor suppressor." (PMID 32328088, 2020). "Therefore, the necroptosis-inhibitory activity of DAPK1 does not necessarily contradict its tumor-suppressing function." (PMID 32366830, 2020). "The aberrant methylated genes in tumor tissue are commonly involved in aspects of cell function such as cell cycle regulation (CDKN2A (also known as p16) and IGF2), DNA mismatch repair (MLH1 and MGMT), apoptosis (DAPK1), cell adhesion (CDH1) and signal transduction (APC and WIF1) in CRC." (PMID 28977860, 2017). "In this study, the frequency of DAPK-1 promoter methylation did not correlate with tumor location." (PMID 26810771, 2016). "Similarly, the aberrant hypermethylation of the DAPK1 gene, involved in programmed cell death and tumor suppression, has been found in OSCC, which per se leads to allowing cancer cells to evade apoptosis, enabling their survival and proliferation, thereby promoting tumor development." (PMID 38067304, 2023). "Thus, it is unclear that as an autophagy inducer, whether or not DAPK1’s function leads to tumor suppression." (PMID 27445685, 2016). "In addition, methylation of MGMT and DAPK1 genes in HCC tumor tissues was significantly higher than normal tissues but not adjacent tissues, revealing that methylation of two genes may play a significant role in the early stage of hepatocarcinogenesis process." (PMID 27835605, 2016). "In contrast to DAPK1 and DAPK3, DAPK2 has not been identified as a tumor suppressor in solid tumors." (PMID 30287790, 2018). "Both tumor suppressor genes BMP7 and DAPK1 are downregulated in the absence of MSP in all 3 isoform overexpressing cell lines." (PMID 27323855, 2016). "None of the patients had a decrease in DAPK1 methylation and an increase in DBC1 methylation and vice versa, indicating that the aberrant methylation is tumor-specific." (PMID 27610206, 2016). "Finally, it may be possible in the future to reconstitute the expression of DAPK1 in patients lacking this important tumor suppressor as delivery of its constitutive kinase domain via a CD22-specific immunoligand has shown remarkable in vitro efficacy and selectivity in preclinical testing." (PMID 27610206, 2016). "The median methylation levels for APAF-1 were 51% in node-negative tumours and 58% in node-positive tumours, the corresponding NIM levels for DAPK-1 being 2 and 9%, respectively." (PMID 17133271, 2006). "Therefore, DAPK-1 methylation may not be a prerequisite for a more aggressive tumour phenotype." (PMID 17133271, 2006).
tumor (continued). "Additionally, it has been found that DAPK-1 is highly expressed in non-cancerous kidney cells compared to s-DAPK-1, understandably so because DAPK-1 serves as a tumour suppressor." (PMID 37372454, 2023). "In contrast to DAPK1, DAPK2 has not been identified as a tumor suppressor in solid tumors." (PMID 34422899, 2021). "Since DAPK1 expression was correlated with expression of SCL16A3, POLOCE and ZBTB16, while the expression levels of these genes were significantly differentially expressed in non-tumor and tumorous liver specimens." (PMID 28740751, 2017). "An inverse correlation has been found between DAXX and DAPK1/3 mRNA expression in a diverse collection of human tumor cell lines and tumor specimens [Submitted], suggesting that DAXX's role as a transcriptional repressor of DAPK1/3 is broadly relevant to tumor biology and is not restricted to PCa." (PMID 26097870, 2015). "While our findings demonstrate the therapeutic potential of DAPK1 reactivation in HGSOC, several limitations should be acknowledged: 1—Our in vitro and 3D organoid models, though informative, may not fully recapitulate the tumor microenvironment or immune interactions observed in vivo." (PMID 40563561, 2025).
cancer (204 papers, 2002 to 2026). A tumor composed of atypical neoplastic, often pleomorphic cells that invade other tissues. "The pro-apoptotic function of DAPK1 is closely associated with the pathogenesis of cancer and neurodegenerative diseases." (PMID 38195518, 2024). "DAPK-1 hypermethylation and loss of its expression have been associated with various types of cancer, including bladder, kidney, gastric, head and neck, thyroid, lung, ovarian, and cervical." (PMID 39081443, 2024). "The association between cancer and DAPK-1 was established through the observation of considerable methylation in the DAPK-1 promoter regions in several types of human tumors, as compared to their corresponding normal tissue samples." (PMID 39081443, 2024). "The loss of DAPK-1 expression in cancer cell lines has been demonstrated to be due to epigenetic silencing via DNA hypermethylation." (PMID 37372454, 2023). "Death-associated protein kinase 1 (DAPK-1) is one of the genes that have shown potential as biomarkers for cancer treatment." (PMID 37372454, 2023). "DAPK1 expression induced autophagy and apoptotic activity in various cancers by causing autophagic cell death via reducing the interaction between Beclin-1, Bcl-2, and Bcl-XL." (PMID 35321516, 2022). "Death-associated protein kinase (DAPK1) was found to participate in the development of various malignant tumors." (PMID 36290392, 2022). "Emerging evidence showed that numerous miRNAs caused DAPK1 deregulation in multiple cancers, for example, miR-103, miR-34a-5p and miR-191 etc." (PMID 34422899, 2021). "Our study demonstrates that DAPK1 is closely associated with Oct4 regulation, which determines cancer stemness." (PMID 34831219, 2021). "DAPK1 is a calcium/calmodulin-dependent Ser/Thr kinase that is involved in cell death, and its deregulation is implicated in cancer and AD." (PMID 32195254, 2020). "Nonetheless, an understanding of the underlying molecular mechanisms that play a major role in DAPk1's transcriptional regulation constitutes a prerequisite to the development of novel therapeutics against cancer and inflammation-associated diseases." (PMID 30783518, 2019). "As such, hypermethylation of the 5′ CpG island of DAPk1's promoter region is common in many cancers and occurs at varying levels, although DAPk1 expression loss can also be a result of homozygous deletion." (PMID 30783518, 2019). "Futhermore, hypermethylation and transcriptional regulation, DAPk1 expression loss can also result from heterozygosity and homozygous deletion of DAPk1 as found in certain types of cancers." (PMID 28976934, 2017). "The loss of DAPk1 and DAPk2 expression in multiple types of human cancer ignited the profound interest in the kinase family regarding their function and involvement in various diseases." (PMID 28976934, 2017). "ALG-2 has been reported to interact with cancer- or apoptosis-associated Ser/Thr-kinases such as Raf-1 and DAPK1 (death-associated protein kinase 1) in a Ca2+-dependent manner but with ASK1 Ca2+-independently." (PMID 27571067, 2016). "The loss and gain-of–function of DAPK1 is associated with various cancer and neurodegenerative diseases respectively." (PMID 27445685, 2016). "Both cancer and neurodegenerative disease have been linked with misregulated autophagy, and to loss- and gain-of-function of DAPK1, respectively." (PMID 27445685, 2016). "Cancer and neurodegenerative diseases have been associated with abnormal apoptosis, autophagy and cell cycle deregulation, as well as loss- and gain-of-function of DAPK-1." (PMID 37372454, 2023). "Since deregulation of DAPK-1 is implicated in the pathogenesis of cancer, altering DAPK-1 expression or activity may be a promising therapeutic strategy against cancer." (PMID 37372454, 2023).
cancer (continued). "However, the precise association based on the molecular mechanism of DAPK1 and TAp63 in various cancer environments still needs to be investigated." (PMID 31336860, 2019). "These factors indicate that the silencing of DAPK1 by such methylation may be associated with cancer progression." (PMID 25435999, 2015). "It was hypothesized that Ded protein, a product of DAPK1 gene, might cause cell immortalization and determine malignancy in cancers." (PMID 24037645, 2013). "Our data suggest that DAPK3 inhibition could be an alternative to ibrutinib treatment in CLL, particularly in cases where resistance is associated with BTK/ PLCγ2 mutations, but also more generally in cancers characterised by DAPK1‐silencing, which is a common marker of poor prognosis." (PMID 32306542, 2020). "We hypothesize that this hallmark of cancer could be partly driven by the DAPK1-ERK axis." (PMID 31772156, 2019). "The downregulation of DAPK1 in cancer tissues compared to their benign counterparts was shown to be correlated with a poor prognosis in the early stages of the disease and was found to originate from promoter methylation." (PMID 40563561, 2025). "To evaluate the therapeutic potential of DAPK1 restoration on patient-derived cancer cells, we transfected primary HGSOC cells with IVT ΔDAPK1 mRNA." (PMID 40563561, 2025). "DAPK1, found in the cancer pathway (hsa05200), is a part of the Ser/Thr kinase family and is an important regulator of cell death and autophagy." (PMID 40088196, 2025). "In a large cohort of 507 ovarian tissues, comparing DAPK1 expression in benign and malignant epithelial ovarian tissues revealed a significant downregulation of DAPK1 in cancer tissues by a factor of 6.1." (PMID 40563561, 2025). "It is natural to infer that hypermethylation of DAPK1 not only silences its gene expression but also contributes to the malignancy state of tumors, making it a potential biomarker for cancer diagnosis and prognosis." (PMID 40918124, 2025). "Data regarding the regulation of s-DAPK-1 in cancer cells is unavailable, particularly in relation to its posttranscriptional regulation." (PMID 40699815, 2025). "Anomalous methylation of p16, DAPK1, and MGMT tumour suppressor genes has been detected in OSCC tissues and linked to early cancer development." (PMID 40027232, 2025). "5-Aza-20-deoxycytidine, a demethylation agent, inhibited cell growth or induced apoptosis by increasing DAPK1 mRNA levels in cancer cell lines." (PMID 39057063, 2024). "The need for early prognostic prediction of this potential for malignant transformation of OLP lesions led the research towards cancer stem cell biomarkers and, in our study, DAPK-1." (PMID 39553125, 2024). "Among the various roles played by DAPK1, DAPK1 has been recently shown to be involved in the cancer metastasis process in various ways." (PMID 39057063, 2024). "DAPK-1 suppression has an impact on apoptosis, which, in turn, contributes to the genesis and progression of cancer." (PMID 39081443, 2024). "Conversely, reduced DAPK1 expression is reported in various cancers, such as lung, breast, colon, and gastric cancers, highlighting its role in tumorigenesis and progression." (PMID 39926603, 2024). "Because regulating DAPK1 expression can affect cancer progression, studies have examined the activation of DAPK1." (PMID 39057063, 2024). "A recent study found that the level of the tumor suppressor DAPK1 is regulated in several ways during cancer metastasis." (PMID 39057063, 2024). "A recent study showed that DAPK1 regulates cancer stem cells in prostate cancer by interacting with the zinc finger E-box-binding homeobox-1 (ZEB1) to inhibit the Hippo/YAP signaling pathway in PCa-CD133(+) cells." (PMID 39057063, 2024). "The downregulation or inactivation of DAPK1 in pituitary tumors and liver cancer was shown to promote cancer progression or make it more aggressive." (PMID 39057063, 2024).
cancer (continued). "DAPK1 hypermethylation (inactivation) and DAPK1 downregulation during the process of metastasis are believed to be meaningful because they link CSCs with cancer aggressiveness." (PMID 39057063, 2024). "Pin1 is expressed to varying degrees in cancer, and the binding of the death domain of DAPK1 to Pin1 inhibits the function of Pin1." (PMID 39057063, 2024). "The involvement of DAPK-1 in carcinogenesis is through its epigenetic silencing via hypermethylation of its promoter, a phenomenon that has been found to occur in most human cancers." (PMID 37372454, 2023). "In conclusion, DAPK-1 is arguably one of the most important genes in cell homeostasis and cancer development." (PMID 37372454, 2023). "Few studies on the role of DAPK1 in MMD have been conducted compared to neurodegenerative diseases or cancer." (PMID 37612316, 2023). "Apoptosis is one of the processes that are affected by DAPK-1 silencing, thus leading to cancer development and progression." (PMID 37372454, 2023). "The molecular basis by which DAPK-1 induces these cell homeostasis-related processes for cancer prevention is less understood; hence, they need to be investigated." (PMID 37372454, 2023). "In summary, we have shown for the first time that PIP increases the sensitivity of BC cells to apoptosis induced by anti-cancer drugs, which is associated with overexpression of specific pro-apoptotic genes (CRADD, DAPK1, FASLG, CD40, and BNIP2)." (PMID 37085653, 2023). "For cancer samples, DAPK1, MLH1 and MALAT1 had higher expression, and MEG3, TIMP3 and SOX1 had lower expression when compared to normal samples." (PMID 35682732, 2022). "A previous study has also shown the inhibitory role of DAPK1 in necroptosis in HT-29 cells, since knockdown or knockout of DAPK1 in such cells increased cancer cell sensitivity to necroptosis." (PMID 36505813, 2022). "As a serine/threonine protein kinase, DAPK1 is considered to be a cancer suppressor gene, which is regulated by calmodulin (CaM) and is a positive regulator of IFN-γ-induced apoptosis." (PMID 35321516, 2022). "DAPK1 is a Ca2+/CaM-regulated serine/threonine protein kinase involved in the regulation of cancer cells from diverse origins." (PMID 35154442, 2022). "For cancer samples, the expression level was higher than in normal samples for DAPK1, MLH1 and MALAT1, and lower for MEG3, TIMP3 and SOX1." (PMID 35682732, 2022). "The role of the tyrosine kinases in inactivating DAPK1 is consistent with previous studies that show high levels of phosphorylation of the vicinal tyrosine residues in cancer as well as fibroblast cells." (PMID 35927990, 2022). "Previous research revealed that DAPK1 is a tumor suppressor gene, and the level of DAPK1 was down regulated in various cancers." (PMID 34422899, 2021). "It has been linked to many cancers, including cSCC, and some of the most frequently hypermethylated genes in cSCC include CADM1, CDH1, and DAPK1." (PMID 34696474, 2021). "We also evaluated cancer cell migration after modulation of DAPK1 in these cells, which decreased significantly in stable DAPK1-overexpressing MDA-T32 and BCPAP cells (p < 0.001 and p < 0.001, respectively)." (PMID 34831219, 2021). "We also analyzed the changes in cancer cell proliferation, migration, and invasion after modulating DAPK1 expression." (PMID 34831219, 2021). "We observed significant inhibition of cancer cell invasion in cells overexpressing DAPK1, but the opposite effect in KD cells." (PMID 34831219, 2021). "Conversely, cancer cell invasion was significantly lower in DAPK1 ΔCaM-overexpressing MDA-T32 and BCPAP cells (p < 0.01 and p < 0.01, respectively)." (PMID 34831219, 2021). "Provided the additional supportive background, the fact that CSF1R and DAPK1 were found to correlate with cancer diseases promoted these compounds as potential antiproliferative molecules." (PMID 31809612, 2020).